GSN (gelsolin)
Diseases named in the same sentence as GSN in open-access papers (continued):
Sharing a sentence is not in itself a finding about the gene and the disease.
osteosarcoma (5 papers, 2016 to 2023). A usually aggressive malignant bone-forming mesenchymal neoplasm, predominantly affecting adolescents and young adults. "Further, Western blotting and enzyme linked immunosorbent assay (ELISA) confirmed decreased levels of gelsolin in the osteosarcoma serum samples." (PMID 28439237, 2017). "Furthermore, downregulation of GSN correlated with a significant decrease in cell invasion in canine OSA8 cells transduced with GSN shRNA as compared to those transduced with scrambled control shRNA demonstrating a direct role for GSN in contributing to the invasive properties of osteosarcoma cells." (PMID 27724924, 2016).
Renal amyloidosis (5 papers, 2016 to 2022). A form of amyloidosis that affects the kidney. "The two recently reported gelsolin gene variants c.580G > A and c.633C > A seem to exclusively cause renal amyloidosis." (PMID 31952544, 2020). "Two novel gelsolin gene variants (c.633C > A, c.580G > A) causing renal amyloidosis have recently been reported in the US." (PMID 31952544, 2020). "A similar approach was here applied to dissect the molecular bases of the pathogenicity of the other variant responsible for gelsolin-related renal amyloidosis." (PMID 29069428, 2018). "Two novel pathological variants of gelsolin have recently been described to be associated with renal amyloidosis containing the following mutations: Asn184 to Lys and Gly167 to Arg (C633 to A and G580 to A, respectively)." (PMID 29069428, 2018). "Followed by G194R and N211K mutations, whose clinical phenotype is different from D214N/Y, mainly gelsolin-related renal amyloidosis." (PMID 33192475, 2020).
viral infection (5 papers, 2013 to 2023). "Equivalently to total cofilin-1 expression, viral infection received a significant decrease of 0.67-fold for cytosolic gelsolin." (PMID 36992512, 2023). "In turn, it is conceivable that HIV-1 regulates actin cytoskeleton reorganization and dynamics for viral infection by acting on the PI4P5-K Iα/PIP2 axis to modulate cytoskeletal molecules such as gelsolin, profilin, filamin-A, and ERM proteins." (PMID 37685911, 2023). "Plasma gelsolin (pGSN) is an actin-binding protein and an innate immune marker involved in disease pathogenesis and viral infections." (PMID 36148234, 2022). "This inhibition of virus-induced receptor clustering may account for the observed inhibition of HIV-1 Env-mediated membrane fusion and early viral infection following the silencing of gelsolin expression." (PMID 23575248, 2013). "Hence, alteration of gelsolin expression or activity accounts for an abnormal HIV-1 Env-mediated cortical actin reorganization that negatively affects early viral infection." (PMID 23575248, 2013). "Thus, it appears that endogenous gelsolin maintains cortical actin dynamic during early viral infection, acting in a pre-fusion step." (PMID 23575248, 2013). "Hence, HIV-1 is unable to reorganize aberrant AFs in the absence of gelsolin, negatively affecting pseudopod formation and CD4/CXCR4-CCR5 redistribution and aggregation, thereby avoiding viral infection." (PMID 37685911, 2023).
corneal lattice dystrophy (4 papers, 2020 to 2025). "This generates amyloidogenic fragments (8 kDa and 5 kDa) of plasma gelsolin, which deposit systemically, leading to symptoms such as corneal lattice dystrophy and neurodegeneration." (PMID 41006687, 2025). "Immunohistochemistry is a useful technique to localize AGel deposits and differentiate gelsolin-related corneal lattice dystrophy (CLD II) from other corneal lattice dystrophies by using antibodies directed against variant gelsolin." (PMID 34206500, 2021).
ischemic stroke (4 papers, 2013 to 2021). A stroke disorder caused by obstruction of blood flow to the brain, due to thrombotic (local blood clot formation) or embolic (due to a blood clot or other material traveling from another site) event. "Previous studies have shown significant predictive values of gelsolin in other acute brain injury including intracerebral hemorrhage, ischemic stroke, and traumatic brain injury." (PMID 23880145, 2013). "Recently, it has been reported that plasma gelsolin levels were also decreased in the patients with traumatic brain injury, ischemic stroke, and intracerebral hemorrhage; in these groups of patients, low gelsolin levels were highly predictive for mortality." (PMID 23880145, 2013).
lymph node metastasis (4 papers, 2018 to 2022). "They noticed that the increased Gelsolin gene expression level was associated with lymph node metastasis, malignant disease progression as well as increased risk of mortality." (PMID 33391377, 2021). "The results showed that reduced Gelsolin and increased Scinderin expression were related to lymph node metastasis." (PMID 32636728, 2020). "Patients with axillary lymph node metastasis may express significant higher level of Villin and Gelsolin genes." (PMID 33391377, 2021). "The mean Gelsolin expression levels in both groups (with and without axillary lymph node metastasis) were 4.13±2.40 and 1.00±0.35, respectively (P<0.001)." (PMID 33391377, 2021). "A sharp increased expression of Scinderin and a reduction of expression of Gelsolin was more significant in samples with positive lymph node metastasis (60.97 %) in contrast with samples with no lymph node metastasis (39.02 %)." (PMID 32636728, 2020).
malaria (4 papers, 2011 to 2023). Malaria is a serious and sometimes fatal disease caused by a parasite that commonly infects a certain type of mosquito which feeds on humans. "In malaria, a variety of serum/plasma proteins bind to HZ crystals such as serum amyloid A, gelsolin, fibrinogen, albumin, and the lipopolysaccharide (LPS)-binding protein." (PMID 31905972, 2019). "This suggests that hemozoin-gelsolin complexes may also contribute to the depressed gelsolin levels observed during malaria." (PMID 22028888, 2011).
protein misfolding diseases (4 papers, 2020 to 2026). "The amyloidogenic gelsolin fragment AGelD187N does not play any physiological role in the body, unlike most aggregating proteins related to other protein misfolding diseases." (PMID 38944121, 2024).
systemic lupus erythematosus (4 papers, 2016 to 2026). An autoimmune multi-organ disease typically associated with vasculopathy and autoantibody production. "Glomerular and tubular gelsolin was detected in lupus patients with nephritis and showed some association with LN classification." (PMID 35208209, 2022).
Arthritis (3 papers, 2021 to 2025). Inflammation of a joint. "The cilium connected proteins C5orf30 and GSN that we found interacting with RA risk variants in FLS were previously shown to be negative regulators of arthritis in mice." (PMID 34433485, 2021). "Since this protein is known to play a role in arthritis, here we investigate how the synovial membrane with its specific synoviocytes contributes to the expression of GSN and how the amount of GSN expressed is modulated by different types of arthritis." (PMID 35327525, 2022). "Assuming that gelsolin can serve as a new prognostic marker for treatment (e.g., therapy more or less aggressive), further studies are needed to investigate the ability of synoviocytes to express GSN and to determine the role of GSN in arthritis." (PMID 35327525, 2022). "In arthritis, GSN is a well-studied protein that is often decreased in blood serum and synovial fluid and therefore serves as a biomarker for these diseases." (PMID 35327525, 2022). "Further investigation is required to focus on how GSN affects joint homeostasis and the significance of reduced GSN expression in adult arthritis and whether the increased GSN levels in JIA should be understood as a response to the onset of arthritis." (PMID 35327525, 2022).
asthma (3 papers, 2011 to 2023). "Here we further supported the association on C5 with allergic asthma and furthermore suggested that the entire 9q33.2 region harbouring also Gelsolin and Rab14 is associated with asthma, thus identifying new candidate risk alleles in genes regulating inflammation and immunomodulation." (PMID 21359210, 2011).
astrocytomas (3 papers, 2016 to 2021). "Gelsolin (Gsn) was also decreased in serum at the pre-symptomatic and symptomatic stages, and decreased circulating gelsolin levels have also been reported in GBM patients while its tissue expression decreased with grade in astrocytomas." (PMID 34641541, 2021).
autoimmune disease (3 papers, 2022 to 2026). A disorder resulting from loss of function or tissue destruction of an organ or multiple organs, arising from humoral or cellular immune responses of the individual to their own tissue constituents. "Plasma gelsolin is recently considered as a diagnostic biomarker in various chronic inflammatory conditions, predictor of autoimmune diseases, and therapeutic target in neurological and neurodegenerative diseases." (PMID 36902587, 2023). "Gelsolin is associated with several autoimmune diseases, and here, we aimed to analyze its usefulness as a serological biomarker for clinical and endoscopic activities in ulcerative colitis." (PMID 35453622, 2022). "In this context, gelsolin and high-density lipoproteins arise as novel biomarkers from the perspective of immunomodulation and their role in the immunopathology of autoimmune diseases." (PMID 41710123, 2026).
breast tumor (3 papers, 2019 to 2024). "Different types of mutations were observed in gelsolin coding regions, and the transcript level was significantly lower in breast tumor tissues compared to control samples, as well as in metastatic patients, compared to disease-free patients at final follow-up." (PMID 39061201, 2024). "NME1 inhibited the actin depolymerizing activity of gelsolin, antagonized gelsolin-stimulated tumor cell migration in vitro, and attenuated its pro-metastatic activity in an in vivo model of breast tumor metastasis." (PMID 37353690, 2023). "LINC00536 was found to be associated with expression of GSN and IQANK1, a ubiquitous actin filament-cleaving protein and a well-known downregulated target in breast tumors." (PMID 31850229, 2019).
cardiac hypertrophy (3 papers, 2018 to 2022). "Myocardial hypertrophy caused by left anterior descending coronary artery ligation is ameliorated in gelsolin knockout mice (GSN−/−)." (PMID 36428995, 2022). "A previous study reported that miR-21 prevents early DCM by attenuating impairments in diastolic dysfunction and cardiac hypertrophy, by reducing the production of ROS via gelsolin." (PMID 33815116, 2021). "This was consistent with the previous studies that overexpression of GSN in H9c2 induced cardiac hypertrophy." (PMID 30180843, 2018). "In myocardial hypertrophy, the protein level of gelsolin is abnormally upregulated." (PMID 36428995, 2022). "In addition, caspase cleavage of the gelsolin fragment plays an important role in cardiac hypertrophy." (PMID 36428995, 2022). "In addition, decreased gelsolin can effectively inhibit the reactivation fetal gene (NPPA and NPPB) and myocardial hypertrophy induced by palmitate or phenylephrine." (PMID 36428995, 2022).
chronic kidney disease (3 papers, 2015 to 2021). Impairment of the renal function secondary to chronic kidney damage persisting for three or more months. "Plasma gelsolin has also been implicated in the development and clinical outcome of patients with chronic kidney diseases (CKD)." (PMID 30149613, 2018). "In this study, we evaluated whether elevated gelsolin levels in patients with chronic kidney disease may be an indication of podocyte damage." (PMID 34948078, 2021). "Enhanced gelsolin levels in chronic kidney disease patients may reflect damaged podocytes and advanced stages of CKD." (PMID 34948078, 2021).
Cirrhosis (3 papers, 2016 to 2025). A chronic disorder of the liver in which liver tissue becomes scarred and is partially replaced by regenerative nodules and fibrotic tissue resulting in loss of liver function. "Differential expression of COL4A4 and PACSIN3 was found in patients with NAFLD and cirrhosis compared to healthy individuals, and GSN, that is associated to HCC, was the most upregulated gene in cirrhosis." (PMID 40489530, 2025). "The upregulated genes between cirrhosis and healthy included GSN, COL4A4, CHI3L1, and GLIS2." (PMID 40489530, 2025).
colorectal adenocarcinoma (3 papers, 2012 to 2023). The most common type of colorectal carcinoma. "This is consistent with earlier observations of prominent gelsolin expression along the invasive front of liver metastases, in contrast to its low expression in primary colorectal adenocarcinomas." (PMID 22927998, 2012).
coronary heart disease (3 papers, 2013 to 2024). "Our previous work indicated that platelet gelsolin is the main platelet differential functional protein between patients of coronary heart disease and healthy people by platelet proteomics." (PMID 23533533, 2013). "Using differential proteomics of platelet, our previous study indicated that platelet gelsolin was the main platelet differential functional proteins between patients with coronary heart disease and healthy people." (PMID 23533533, 2013).
dementia (3 papers, 2013 to 2022). Loss of intellectual abilities interfering with an individual's social and occupational functions. "Our study also indicates a crucial role of AHNAK in processes of aging-related dementia, and we hypothesize that the Cb exploits proteins such as CEND1 or GSN to fight against neurodegeneration." (PMID 24008896, 2013).
diabetic cardiomyopathy (3 papers, 2018 to 2022). Diabetic cardiomyopathy is a disorder of the heart muscle in people with diabetes. "MiR-21 was documented to mediate also cardioprotection against diabetic cardiomyopathy-induced diastolic dysfunction, likely via targeting gelsolin, an actin-binding protein that is a key regulator of actin filament assembly and disassembly." (PMID 31973111, 2020). "Our findings reveal a new role of miR-21 in attenuating diabetic cardiomyopathy by targeting gelsolin, and provide a molecular basis for developing a miRNA-based therapy against diabetic cardiomyopathy." (PMID 30180843, 2018). "Thus attenuation of cardiac hypertrophy by decreased ROS production and improved NO release via gelsolin represent a new therapeutic strategy to treat diabetic cardiomyopathy." (PMID 31973111, 2020). "Moreover, down-regulation of gelsolin by siRNA also attenuated the early phase of diabetic cardiomyopathy." (PMID 30180843, 2018). "Though we identified GSN as an important target of miR-21 in diabetic cardiomyopathy, there may be still other targets of miR-21." (PMID 30180843, 2018).
dilated cardiomyopathy (3 papers, 2018 to 2023). Cardiomyopathy which is characterized by dilation and contractile dysfunction of the left and right ventricles. "The severing activity of gelsolin was found to be stimulated by mechanical loading in dilated cardiomyopathy, whereas unloading by left-ventricular assist devices therapy restored severing." (PMID 33303625, 2021). "Accordingly, loss of PI3Kα, the key PIP3-producing enzyme in the heart, increases gelsolin-mediated actin-severing activities in the myocardium in vivo, resulting in dilated cardiomyopathy in response to pressure-overload." (PMID 30568254, 2018).
gastric tumor (3 papers, 2020 to 2022). "The expression levels of two important actin-binding proteins, Gelsolin and Scinderin, were studied in gastric tumor and the adjacent normal tissue in this study." (PMID 32636728, 2020).
liver cancer (3 papers, 2018 to 2023). An epithelial or non-epithelial malignant neoplasm that arises from the liver. "In liver cancer, patients have a poor prognosis with high GSN expression, possibly because GSN overexpression increases the aggressiveness of cancer cells via controlling epithelial-mesenchymal transition (EMT)." (PMID 37035750, 2023). "Gelsolin (GSN) is an important molecule that mediates metastasis and invasion of liver cancer cells." (PMID 35096574, 2021).
liver disease (3 papers, 2019 to 2025). "Interestingly, many of the genes linked to the differentially methylated CpGs have been associated with liver disease progression (eg, DCP2, TRPV3, ARRB1, KCNIP4, MIR10A) and cancer formation or progression (eg, MTHFR, GRIK2, GSN, HOX3, KCNMA1)." (PMID 40275933, 2025).
lung squamous cell carcinoma (3 papers, 2022 to 2024). "Findings of recent comprehensive database analyses showed that GSN promoter is hypermethylated in many cancers, including head and neck squamous carcinoma and lung squamous cell carcinoma." (PMID 39261905, 2024).
multiple sclerosis (3 papers, 2017 to 2022). A progressive autoimmune disorder affecting the central nervous system resulting in demyelination. "The decrease of gelsolin (GSN) in the blood has been reported in multiple sclerosis (MS) patients and experimental allergic encephalomyelitis (EAE) animals, but the protective effect of GSN on EAE/MS lacks of evidence." (PMID 28377587, 2017). "The decrease of gelsolin in the blood has been also reported in multiple sclerosis (MS) patients." (PMID 30149613, 2018). "More detailed research using a mouse model of multiple sclerosis, i.e., experimental autoimmune encephalomyelitis (EAE), confirmed a decrease of plasma gelsolin with subsequent increase of GSN in acute EAE brains." (PMID 30149613, 2018).
Myocardial fibrosis (3 papers, 2018 to 2023). "Gelsolin (GSN), a protein that severs and caps actin filaments and plays a pivotal role in regulating actin assembly, has been reported to be involved in fibroblast activation during the development of myocardial fibrosis." (PMID 38203265, 2023). "While decreased cytoskeletal remodeling in cardiomyocytes in vivo might have contributed to decreased myocardial fibrosis due to less mechanical stress, the role of gelsolin-mediated cytoskeletal remodeling in cardiac fibroblast and its implications in DCM warrant further investigation." (PMID 30568254, 2018). "Although our data suggest a key regulation of gelsolin activity by PI3Kα-generated PIP3 in cardiomyocytes, this phenomenon may also exist in cardiac fibroblasts and may have contributed to the reduced myocardial fibrosis seen in the pressure-overloaded GSNKO mice." (PMID 30568254, 2018).
thyroid cancer (3 papers, 2021 to 2023). "In contrast, cholangiocarcinoma (CHOL), kidney renal clear cell carcinoma (KIRC), liver hepatocellular carcinoma (LIHC) and thyroid carcinoma (THCA) GSN mRNA expression patterns were elevated compared with the matching healthy tissue levels." (PMID 37035750, 2023). "Interestingly, in the TRPV/PV mouse model of thyroid cancer, gelsolin is functionally important in Akt-dependent cancer progression, suggesting a functional role for this particular gene in thyroid cancer biology." (PMID 34238982, 2021).
acute lung injury (2 papers, 2018 to 2019). A condition of lung damage that is characterized by bilateral pulmonary infiltrates (pulmonary edema) rich in neutrophils, and in the absence of clinical heart failure. "To date, a few (mainly mouse model-based) studies focused on evaluating the therapeutic efficiency of gelsolin repletion in subjects with insult-induced acute lung injury." (PMID 30149613, 2018). "An interesting study focused on the predictive effectiveness of plasma gelsolin in patients below 3 years of age developing cardiopulmonary bypass-induced acute lung injury (CPB-ALI) as the result of cardiac surgery." (PMID 30149613, 2018). "Exogenous gelsolin was also found to limit neutrophil migration, scavenge soluble pro-inflammatory mediators, and inhibit neutrophil adhesion to endothelial surfaces in a mouse model of acute lung injury." (PMID 30711007, 2019).